MUC5AC (mucin 5AC, oligomeric mucus/gel-forming)
Diseases named in the same sentence as MUC5AC in open-access papers (continued):
Sharing a sentence is not in itself a finding about the gene and the disease.
asthma (continued). "Although the number of goblet cells expressing MUC5B was similar in asthma airways with mucus plugs, unplugged asthma airways, and lung disease–free control airways, the number of goblet cells expressing MUC5AC was significantly higher in asthma airways occluded with mucus plugs." (PMID 40091838, 2025). "MUC5AC expression is higher in patients with asthma than in healthy individuals." (PMID 40709340, 2025). "Therefore, regulating MUC5B expression is as important as regulating MUC5AC for effective asthma treatment." (PMID 40869396, 2025). "Compared to the AM and SRAM groups, the CAM and CSRAM group showed a further significant increase in MUC5AC expression, confirming that cold stimulation could aggravate the severity of asthma in mice." (PMID 39201796, 2024). "Additionally, muc5ac is highly expressed in the epithelial cells of human patients with asthma, where mucus cell hyperplasia, originating from a novel mucociliary cell state, and goblet cell hyperplasia have been observed." (PMID 39391497, 2024). "In our established mouse asthma model, the cold stimulation exacerbated mucus hypersecretion with goblet cell hyperplasia and elevated MUC5AC expression, which is consistent with the effects of cold stimulation on human bronchial epithelial cells, or AECOPD models." (PMID 39201796, 2024). "Many conditions affecting the airways, such as asthma, CF, and COPD, cause an increase in MUC5AC." (PMID 39057040, 2024). "Other studies on human airway cells aimed to explain two key aspects of asthmatic pathology: (i) the reprogramming of epithelial cells, leading to increased MUC5AC expression and mucus secretion, and (ii) the effects of IL-13 on epithelial cells, which are related to IL-13-induced asthma." (PMID 39684345, 2024). "Notably, in an ovalbumin-induced murine model of asthma, lovastatin suppresses goblet-cell hyperplasia and inhibits MUC5AC protein and gene expression." (PMID 37241840, 2023). "The hypersecretion of airway mucus is an important physiological and clinical symptom of various respiratory tract diseases, such as chronic bronchitis and asthma, and airway stimuli, such as antigens, bacteria, and particles, upregulate the MUC5AC and MUC2 genes." (PMID 37687271, 2023). "In other disease settings, MUC5AC mRNA is increased in asthma, whereas MUC5B levels are decreased." (PMID 37005656, 2023). "Serum IgE and MUC5AC expression levels were lower than those in the asthma group." (PMID 38155957, 2023). "To determine the effects of IL-31 on the expression of asthma-associated genes, we quantified the expression of genes associated with inflammation (IFNγ, TNF-α, IL-6, and IL-17) and Th2 responses (IL-4, IL-13, ARG1, MUC4, and MUC5AC)." (PMID 38081868, 2023). "Furthermore, expression of genes whose expression correlates with asthma, including Il9, Il4, Il13, Ccl11, Ccl24, and Muc5ac, was much lower in recipients of Id1 cKO Th9 cells." (PMID 37867222, 2023). "Additionally, we observed that SZYQD treatment effectively suppressed the overexpression of MUC5AC, which is considered a key pathophysiological abnormality in asthma." (PMID 38093206, 2023). "Mucin 5AC (MUC5AC), major constituent of mucus, is predominantly expressed by airway epithelial cells and its up regulated expression has been reported in chronic inflammatory diseases including asthma." (PMID 37316684, 2023). "The significant signal at MUC2 in our analysis was not independent of the previously reported moderate-to-severe asthma signal for which MUC5AC was implicated as the most likely causal gene using gene expression data from bronchial epithelial cells." (PMID 37263751, 2023). "Unsurprisingly, HDM-treated airways had drastically increased expression of Muc5ac in the epithelium and significant immune cell infiltration near airways as shown by Ly-6G + neutrophils (immune cell type notoriously increased in many patients with asthma)." (PMID 37928904, 2023).
asthma (continued). "Mucin 5AC (MUC5AC) is excessively secreted in the respiratory tract of patients with asthma." (PMID 36188610, 2022). "MUC5AC upregulation is an important characteristic of goblet cell metaplasia and mucus hypersecretion, which is always observed in airway inflammation diseases, such as asthma and COPD." (PMID 36193088, 2022). "Specifically, IL-13 stimulation of both mouse and human airway epithelia is sufficient to drive increases in the expression of MUC5AC, an airway mucin gene, and mucus-metaplastic transformation of the tissue, both of which contribute to the airway obstruction seen in asthma." (PMID 35347136, 2022). "Moreover, it has been demonstrated that leptin has improved cytokine production by lung fibroblasts, and MUC5AC production by IL-13 in human bronchial epithelial cells, contributing to the worsening of asthma in obese individuals." (PMID 36613991, 2022). "Furthermore, elevated levels of MUC5AC contributed to the development of AHR in an asthma animal model." (PMID 36012669, 2022). "The expressions of inflammatory cytokines, MUC5AC and ICAM-1 were determined by quantitative reverse transcription PCR (RT-qPCR), enzyme-linked immunosorbent assay (ELISA) and Western blot after TXL was exposed to an in vitro asthma model." (PMID 35000533, 2022). "During asthma progression, MUC5AC is specifically expressed in goblet cells." (PMID 35344278, 2022). "In addition, mucus hypersecretion has been related to asthma, as there is evidence of an increased MUC5AC presence in severe asthma epithelial cells." (PMID 35887589, 2022). "The activity of Muc5ac may lead to mucus blockage and airway inflammation worsening asthma symptoms." (PMID 36188624, 2022). "IL-17A is also able to induce the expression of the mucin genes MUC5AC and MUC5B in bronchial epithelial cells in vitro, and enhanced expression of IL-17A correlates with MUC5AC expression in a mouse model experimental asthma after infection with respiratory syncytial virus (RSV)." (PMID 35883573, 2022). "Sputum plugs from people with severe asthma have previously been shown to contain more MUC5AC than MUC5B, which may have contributed to the increased detection of MUC5AC versus MUC5B in our studies." (PMID 35239513, 2022). "In addition, the study showed that the expression of MUC5AC was also reduced after treatment with dexamethasone in asthma patients, and dexamethasone can also inhibit the expression of IL-2 and IFN-γ." (PMID 35578178, 2022). "In asthma, the expression of MUC5AC is upregulated together with stimulated mucin secretion." (PMID 34276407, 2021). "Furthermore, in the airway epithelial dataset analyzed, MUC5AC showed a significant increase in gene expression in patients with severe asthma." (PMID 35386986, 2021). "MUC5AC is hyperexpressed from goblet cells and increased airway mucus in asthma patients." (PMID 34504957, 2021). "Cockroach allergen induced Muc5ac overexpression in HBECs and airways of asthma mouse model." (PMID 34868022, 2021). "Interestingly, the loss of FOXP1 and FOXP4 in the epithelium of patients with a non-Th2 asthma phenotype induces ectopic NPY production and other proteins associated with airway remodeling, such as MUC5AC." (PMID 34055794, 2021). "While evidence has shown that Muc5ac overexpression leads to the development of airway mucus plugging, AHR, and asthma exacerbations, the mechanisms underlying development and immune regulation of mucus production in response to allergens are not fully unveiled." (PMID 34868022, 2021). "Moreover, the mucin score and expression of Muc5ac, which is localized to goblet cells in the surface epithelium and contributes to mucus production that correlates with asthma pathogenesis, were significantly improved in the M-16V diet group." (PMID 32915886, 2020).
asthma (continued). "Altered expression of the pathogenic mucin MUC5AC potentially contributes to mucus plugging and airway obstruction, GATA3 is a transcription factor linked to the T cell response in asthma and eosinophilia, and the KIAA1109 locus has previously been associated with allergic sensitization." (PMID 32060620, 2020). "Reduction in MUC5AC secretion induced by type IV collagen is important in treating asthma." (PMID 31737795, 2019). "Of the 24 signals, after exclusion of FLG, three were novel for asthma: the sentinel SNP rs10905284 in GATA3 (coded allele A, odds ratio [OR] 0·90, 95% CI 0·88–0·93; p=1·76 × 10−10) and rs11603634 in the MUC5AC region (coded allele G, OR 1·09, 1·06–1·12; p=2·32 × 10−8)." (PMID 30552067, 2019). "Among them, MUC5AC is a major mucin glycoprotein and is overproduced in asthma." (PMID 31831011, 2019). "Therefore, regulation of MUC5AC expression in airway epithelial cells is a target for asthma treatment." (PMID 31330806, 2019). "MUC5AC is a major mucin glycoprotein that is overproduced in asthma." (PMID 31831011, 2019). "Although speculative, this finding might suggest that VIP has an inhibitory role on muc5AC expression in asthma." (PMID 30081920, 2018). "Interestingly, in asthma, MUC5AC has been shown to tether to the epithelium, which has been implicated in mucociliary dysfunction and mucus plug formation." (PMID 30154090, 2018). "However, a role for MUC5AC in asthma pathogenesis was established using models of allergic asthma (ovalbumin sensitization and challenge and exposure to Aspergillus oryzae extract (AOE))." (PMID 29186064, 2017). "Many individuals with asthma have increased MUC5AC mRNA levels but decreased MUC5B mRNA levels." (PMID 29186064, 2017). "Interestingly, within the asthma cohort, a higher ratio of MUC5AC to MUC5B correlated with type 2 inflammation (>2% eosinophils)." (PMID 29186064, 2017). "Deregulation of MUC5AC is implicated in a number of nonneoplastic diseases, including cystic fibrosis, chronic obstructive pulmonary disease, asthma, inflammatory bowel disease, and a variety of cancers." (PMID 28430953, 2016). "Importantly, MUC5AC protein expression level showed asthma-related differences both at vehicle treated baseline (p = 0.05) and after viral infection (p = 0.01)." (PMID 25706956, 2015). "In asthmatic mice, mucus overproduction is accompanied by an increased pendrin expression at the apical surface of bronchial epithelial cells, and in pendrin overexpression cell models, production of MUC5AC, a major mucus protein in asthma and COPD patients, is increased." (PMID 26612971, 2015). "To assess whether expression of MUC5AC-core genes were correlated with MUC5AC in this asthma study, we performed genome-wide correlation analysis to MUC5AC gene expression." (PMID 22676183, 2012). "MUC5AC is a major mucin in airway secretions of healthy subjects, and it is often up-regulated under a variety of pathogenic conditions, including CF, COPD, smoking, and asthma." (PMID 21998660, 2011). "Furthermore, type 2 cytokines are a major regulator of mucin gene expression in an in vivo model and, more importantly, as IL-4 and IL-13 facilitated MUC2 and MUC5AC transcription by activating either the STAT6 or NF-κB pathways with ovalbumin (OVA) in the asthma model." (PMID 36835646, 2023). "FUT2 may play a key role in MUC5AC regulation leading to excess mucus production or its increased viscosity, a common characteristic observed in patients with airway obstructive diseases including asthma, bronchitis and COPD." (PMID 37263751, 2023). "In addition, Ccl11, Ccl24, and Muc5ac, which correlate with asthma, decreased in Id1 cKO mice." (PMID 37867222, 2023). "Furthermore, the effects of SZYQD and its active ingredients were tested in vitro for regulating inflammation and MUC5AC expression (two main pathophysiologic abnormalities of asthma) in macrophages and airway epithelial cells by using Real-time PCR and western blotting." (PMID 38093206, 2023).
asthma (continued). "Similarly, MUC5AC was expressed at higher levels in WT mice than in Elk4 KO mice with asthma." (PMID 37529050, 2023). "Neutrophil inflammation stimulated T1 or T17 cell release in T2-low asthma and induced Muc5ac and Muc5b expression in bronchial epithelial cells, which led to goblet cell proliferation, airway remodeling, glucocorticoid resistance, and the occurrence and development of severe or refractory asthma." (PMID 35685599, 2022). "Therefore, the antioxidant therapy might be useful in the control of MUC5AC production in asthma treatment." (PMID 34504957, 2021). "Thus, Muc5ac, but not Muc5b, may be a major airway mucin selectively responding to cockroach allergen, highlighting that study targeting Muc5ac may have therapeutic potential in unplugging the airway mucus in asthma." (PMID 34868022, 2021). "Muc5ac is the predominant mucin and mainly expressed in the upper airways, trachea, and bronchi, and tethering of Muc5ac to secreting club cells impairs mucus transport, consequently leading to the airway mucus plugging and progressive airway obstruction in asthma." (PMID 34868022, 2021). "Furthermore, EGFR, which is also overexpressed in asthma, also induces the expression of MUC5AC." (PMID 32411147, 2020). "Therefore, examining expression of muc5AC and muc5B in the sputum of people with asthma provided tachykinin receptor antagonists might be especially important." (PMID 30081920, 2018). "This was confirmed in our second cohort of participants, with samples from individuals with severe asthma exhibiting higher MUC5B expression and a tendency toward increased MUC5AC expression." (PMID 40399607, 2025). "DiABZI induced an increased release of lactate dehydrogenase (LDH), IFNα, IFNβ, IFNλ, CXCL10, IL‐6 and TNFα protein and overexpression of MUC5AC transcript in healthy epithelial cells sensitized with HDM, and less in epithelial cells from patient with asthma." (PMID 39466641, 2025). "Suppression of excessively secreted MUC5AC and MUC5B is expected to alleviate airway narrowing and asthma symptoms." (PMID 40869396, 2025). "A characteristic of asthma is the altered MUC5B:MUC5AC ratio, with MUC5AC being more predominant in asthmatic sputum." (PMID 41303221, 2025). "Enhanced production of mucin 5AC (MUC5AC) due to goblet cell metaplasia, paired with airway remodeling and inflammation, drive airway morbidity and mortality in asthma." (PMID 38711951, 2024). "Sputum eosinophil percentages were higher in the asthma group (1.02%) compared to the COPD (0.25%) group, and Spearman’s correlation tests confirmed that G’ and G’’ were positively correlated with MUC5AC protein concentration." (PMID 38339210, 2024). "Our results show that YPL-001 and its iridoids suppress the TNF/NF-κB/MUC5AC and PMA/PKCδ/EGR-1 cascades, which are important signaling pathways involved in inflammatory lung diseases, including COPD and asthma." (PMID 37108390, 2023). "Mucus secretion was also reduced, and the downregulation of two key mucins, MUC5AC and MUC5B, which are integral components of mucus dysfunction in asthma, was observed in the PP121-treated mice." (PMID 37936054, 2023). "Given that previous studies have identified eQTL for MUC5AC in asthma and MUC5B in IPF located near the genes themselves (“local eQTL”), one potential a priori prediction could have been that these same variants would be associated with MUC5AC and MUC5B protein concentrations." (PMID 37352370, 2023). "We suggest that one of the mechanisms by which GSZC granules improve airway inflammation is intervention in the MUC5AC/EGFR signaling pathway, and inhibition of mucus hypersecretion in the airways of rats suffering from asthma." (PMID 36699060, 2022). "Therefore, H19 inhibition may alleviates the development of asthma by downregulating Muc5ac." (PMID 36188624, 2022).
asthma (continued). "The most influential nodes (Fn1, Igf1, Ccl2, C3, Timp1, Cxcl12, Ccl4, Ccr2, Spp1, C3ar1, Cat, Cyp2e1, Muc5ac, Muc5b) were selected for further validation in the OVA-induced asthma and post-asthmatic fibrosis murine model." (PMID 35625754, 2022). "The level of MUC5AC and MUC5B has been found increased in respiratory diseases like asthma and COPD." (PMID 35770160, 2022). "In the HDM-induced mouse asthma model, we found that the HDM extract promoted airway hyperresponsiveness (AHR), MUC5AC, and allergen-specific IgE production as well as IL-5 and IL-13 for recruiting inflammatory cells." (PMID 36012669, 2022). "MUC5AC is crucial for airway eosinophil inflammation and AHR, and the levels of sputum MUC5AC in patients with mild asthma before steroid treatment were higher, when compared to that in the healthy control group." (PMID 35903102, 2022). "Since the sNASP/TRAF6 axis is critical for in vitro MUC5AC production, we evaluated the effect of the PEP-NASP peptide on mucus hypersecretion in vivo using an HDM-induced asthma model." (PMID 36012669, 2022). "CP and OA were shown to significantly inhibit airway and lung inflammation, mucus secretion, lymphocytes, neutrophil and eosinophil infiltration, AHR, and inflammatory mediators such as IL-5, IL-13, CCR3, MUC5AC, and COX-2 in the mouse model of asthma." (PMID 33806085, 2021). "In bronchoalveolar lavage (BAL) fluid from patients with mild-to-moderate asthma, TCEP rapidly depolymerizes MUC5AC and MUC5B, demonstrating the presence of targets in asthma patients even under stable disease conditions." (PMID 33431872, 2021). "Phenotype-related differences are also observed in mucins, as MUC5AC and MUC5B overexpression is present in all asthma phenotypes but with enhanced increases in mixed and neutrophilic asthma." (PMID 34248677, 2021). "In the context of asthma, AhR activation by TCDD or benzo[a]pyrene (B[a]P) can be pro-inflammatory and induce MUC5AC expression, leading to mucus hypersecretion, airway remodeling, dysregulation of antigen-presenting cells, and exacerbation of asthma." (PMID 34744763, 2021). "Drugs that target MUC5AC (ENSITUXIMAB) and STAT6 (CHEMBL363332 and CHEMBL1374370) have emerged as potential avenues of future research via repurposing for severe asthma and show these two proteins are viable therapeutic targets." (PMID 35386986, 2021). "Systemically administered rapamycin reduces Muc5ac and CLCA3 in the airways in a mouse model of asthma." (PMID 33255287, 2020). "In asthma, the proportion of MUC5B relative to MUC5AC often decreased along with the expression of a low-charge form of MUC5B." (PMID 32411147, 2020). "Nevertheless, these data appear contradictory to previous reports suggesting that TMEM16A plays a key role in mucus production, namely, in asthma where both TMEM16A and MUC5AC are concomitantly up-regulated by IL-4 or IL-13 induction." (PMID 31732694, 2019). "Among them, MUC5AC is proved to be the major subfamily, and overproduction of airway mucins (especially MUC5AC or mucin-2 (MUC2)) is signature of human asthma and murine models of asthma." (PMID 31330806, 2019). "To further explore the effect of excessive ROS generation on autophagy activation and the downstream MUC5AC expression, we used NAC to inhibit the oxidant stress in asthma mice models." (PMID 32082074, 2019). "We quantified the principal airway mucins MUC5AC and MUC5B in the sputum of age-matched children with acute and stable asthma and healthy control subjects by using Western blotting." (PMID 28716644, 2017). "Further studies would benefit from more information regarding viral exposure during acute asthma exacerbation and from measuring the concentration of MUC5AC and MUC5B during an acute asthma exacerbation and at recovery in the same patient." (PMID 28716644, 2017). "MUC5AC and MUC5B gene expression is altered in asthma, and recent work sheds light on their contribution to asthma pathogenesis." (PMID 29186064, 2017).